USP11 (ubiquitin specific peptidase 11)
Description:
Protease that can remove conjugated ubiquitin from target proteins and polyubiquitin chains. Inhibits the degradation of target proteins by the proteasome. Cleaves preferentially 'Lys-6' and 'Lys-63'-linked ubiquitin chains. Has lower activity with 'Lys-11' and 'Lys-33'-linked ubiquitin chains, and extremely low activity with 'Lys-27', 'Lys-29' and 'Lys-48'-linked ubiquitin chains (in vitro). Plays a role in the regulation of pathways leading to NF-kappa-B activation. Plays a role in the regulation of DNA repair after double-stranded DNA breaks. Acts as a chromatin regulator via its association with the Polycomb group (PcG) multiprotein PRC1-like complex; may act by deubiquitinating components of the PRC1-like complex. Promotes cell proliferation by deubiquitinating phosphorylated E2F1.
Synonyms: UHX1
Tractability: PROTAC: ubiquitination databases record sites on it; its protein half-life has been measured.
Target class: Enzyme; Hydrolase
Gene: Protein-coding gene on chromosome X (47,232,866 to 47,248,328, forward strand). Ensembl gene ENSG00000102226.
Subcellular location: Nucleus; Cytoplasm; Chromosome
Subcellular location (Human Protein Atlas): Nucleoplasm; Cytosol
Pathways (Reactome):
Metabolism of proteins: Association of TriC/CCT with target proteins during biosynthesis; Ub-specific processing proteases
Gene Ontology:
Molecular function: cysteine-type deubiquitinase activity; cysteine-type endopeptidase activity; protein binding; transcription corepressor binding
Biological process: protein deubiquitination
Cellular component: chromosome; cytoplasm; cytosol; nucleoplasm; nucleus
Homologues: Orthologues: chimpanzee USP11 (97% identical), macaque USP11 (92% identical), rabbit USP11 (87% identical), guinea pig USP11 (83% identical), rat Cdk16 (82% identical), mouse Usp11 (82% identical), pig USP11 (78% identical), dog USP11 (76% identical), zebrafish usp11 (55% identical). Paralogues in human: USP15 (47% identical), USP4 (46% identical), USP32 (27% identical), USP19 (27% identical), USP6 (24% identical), USP8 (23% identical), USP31 (21% identical), USP9X (19% identical), USP43 (19% identical), USP9Y (19% identical), USP24 (19% identical), USP2 (17% identical), and 59 more.
Diseases named in the same sentence as USP11 in open-access papers:
USP11 is named in the same sentence as 84 diseases in open-access papers, as found by Europe PMC text mining. Sharing a sentence is not in itself a finding about the gene and the disease. The quoted sentences say what the papers report.
breast cancer (22 papers, 2014 to 2025). A primary or metastatic malignant neoplasm involving the breast. "By using these mutant mice, cell lines, and human USP11-deficient and -proficient breast cancer tissues, we tested how USP11 controls mammary cell fate." (PMID 39270819, 2024). "Considering that USP11 is an X chromosome-linked gene, it is important to uncover the function and mechanisms of USP11 in controlling female breast cancer development and progression in vivo." (PMID 39270819, 2024). "On the one hand, it can be used as a prognostic factor after neoadjuvant therapy in breast cancer patients; low USP11 expression is independently associated with better survival prognosis." (PMID 35359344, 2022). "High expression of USP11 is associated with poor prognosis of colorectal and breast cancer." (PMID 38007584, 2024). "Moreover, USP11 is implicated in breast cancer initiation and progression as it inhibits cell growth and survival by repressing Erα transcriptional activity." (PMID 39201539, 2024). "Human breast cancers are also associated with diminished USP11 expression." (PMID 38139829, 2023). "USP11 might be a potential therapeutic target for breast cancer patients with ERα mutations and chemotherapy resistance." (PMID 35715413, 2022). "Moreover, the deubiquitination of cell cycle-associated cyclin D1 by USP11 has been suggested to be associated with poor survival in ERα+ breast cancer patients." (PMID 35884607, 2022). "Breast cancer patients expressing high levels of PRMT1 but low levels of USP11 are associated with a poor survival rate, which could be a consequence of defective end-resection thereby favouring error-prone NHEJ and genome instability." (PMID 34728620, 2021). "Regarding the function of USP11 in breast cancer, it, also confusingly, promotes breast cancer cell proliferation and tumorigenesis by stabilizing XIAP and cytoplasmic p21, and inhibits breast cancer cell proliferation through deubiquitination of PTEN." (PMID 39270819, 2024). "In human breast cancers, the expression of USP11 was positively correlated with that of E-cadherin and high USP11 predicted better recurrence-free survival." (PMID 39270819, 2024). "We found that endogenous E-cadherin was co-immunoprecipitated with USP11, and reciprocally, endogenous USP11 was also co-immunoprecipitated with E-cadherin, indicating that USP11 and E-cadherin bind to each other in human breast cancer cells." (PMID 39270819, 2024). "In this study, we investigated the effect of USP11 in regulating mammary cell differentiation by using Usp11 knockout mice, breast cancer cell lines, and human breast cancer samples." (PMID 39270819, 2024). "We found that Usp11 was predominantly expressed in luminal epithelial cells in mice, and the protein levels of Usp11 and E-cadherin were positively correlated in human breast cancer samples." (PMID 39270819, 2024). "The in vivo interaction between Usp11 and E-cadherin was also observed in mouse mammary tumor cells." (PMID 39270819, 2024). "Increased USP11 levels can promote the in vitro growth and in vivo metastasis of breast cancer and colorectal cells." (PMID 38007584, 2024). "We generated Usp11 knockout mice and breast cancer cell lines expressing wild-type (WT) and mutant forms of USP11." (PMID 39270819, 2024). "We discovered that loss of Usp11 reduced the expression of E-cadherin in MECs; therefore, we wanted to investigate if Usp11 controls the differentiation of luminal-type breast cancer cells." (PMID 39270819, 2024). "Mitoxantrone, approved by the US FDA as a USP11 inhibitor, is undergoing numerous phase I/II trials targeting conditions including neoplasms, acute myeloid leukemia, MS, and breast cancer." (PMID 39678489, 2024). "We demonstrated that USP11 maintains the luminal fate of mammary tumor cells, thereby suppressing mammary tumorigenesis." (PMID 39270819, 2024).
breast cancer (continued). "Consistent with our results in mice, these data indicate that the expression of USP11 is positively correlated with E-cadherin in human breast cancers and that USP11 functions as a tumor suppressor in breast cancer." (PMID 39270819, 2024). "In human breast cancers, expression of USP11 was positively correlated with that of E-cadherin, and high USP11 predicted better recurrence-free survival." (PMID 39270819, 2024). "Our findings provide compelling genetic and biochemical evidence that USP11 not only promotes DNA damage repair but also deubiquitinates E-cadherin and maintains the luminal features of mammary tumor cells, leading to the suppression of breast cancer." (PMID 39270819, 2024). "It has been reported that USP11 was highly expressed in various cancerous tissues such as lung cancer, breast cancer, and ovarian cancer, and promoted the progression of tumors." (PMID 39617751, 2024). "Meanwhile, the expression levels of p21 and USP11 were detected in 45 pairs of breast cancer tissues and adjacent normal tissues." (PMID 35414784, 2022). "Both p21 and USP11 were significantly more highly expressed in clinical breast cancer tissues than in normal breast tissues." (PMID 35414784, 2022). "In this study, we found that there was a strong correlation between p21 and USP11 in the cytoplasm of breast cancer tissues and cells." (PMID 35414784, 2022). "Although the complicated role of USP11 in the occurrence, development and drug resistance of breast cancer needs more and more rigorous researches." (PMID 35715413, 2022). "Taken together, these data demonstrate that USP11 promotes breast cancer cell growth in vivo through cytoplasmic p21, and USP11 inhibitor MTX has promise for potential applications in the treatment of breast cancer." (PMID 35414784, 2022). "To further test the feasibility of developing USP11 inhibitor for breast cancer therapy, we used the USP11 inhibitor MTX to treat mice for two weeks." (PMID 35414784, 2022). "Our findings provide the first evidence that ubiquitinated p21 in the cytoplasm can be recycled through USP11-mediated deubiquitination, and we identified the USP11-p21 axis in the cytoplasm as a potential therapeutic target for breast cancer control." (PMID 35414784, 2022). "In agreement with previous studies 26, 43, our data showed that both p21 and USP11 were mainly localized in the cytoplasm of breast cancer tissues." (PMID 35414784, 2022). "USP11 positively regulates ERα transcriptional activity in breast cancer cells in an E2-dependent manner." (PMID 35884607, 2022). "To investigate the potential physiological and pathological functions of p21 and USP11 in breast cancer, we performed bioinformatic analysis using the Clinical Proteomic Tumor Analysis Consortium (CPTAC) dataset." (PMID 35414784, 2022). "Functionally, USP11-mediated stabilization of cytoplasmic p21 induced breast cancer cell proliferation in vitro and in vivo." (PMID 35414784, 2022). "Targeting USP11 is an excellent strategy for different breast cancer subtypes, and USP11 also is a potential predictive and prognostic biomarker for breast cancer progression and drug resistance." (PMID 35715413, 2022). "In contrast, USP11 plays a tumor-promoting role in hepatocellular carcinoma 40, melanoma 41, gastric cancer 42, and breast cancer." (PMID 35414784, 2022). "Taken together, these data indicate that USP11 interacts with p21 in the cytoplasm of breast cancer cells." (PMID 35414784, 2022). "As a result, USP11-mediated stabilization of cytoplasmic p21 promoted the proliferation of breast cancer cells." (PMID 35414784, 2022). "In a cohort analysis of breast cancer patients, the high expression of USP11 was significantly correlated with the low survival rate of ERα-positive patients." (PMID 35359344, 2022). "All above researches imply that USP11 not only significantly affects breast cancer progression but also mediates chemotherapy drugs resistance." (PMID 35715413, 2022).
breast cancer (continued). "Upregulation of USP11 can increase the in vitro invasion and in vivo metastasis of breast cancer cells." (PMID 35359344, 2022). "USP11 was mainly localized in the cytoplasm of breast cancer cells, which is different from previous studies describing its nuclear location 34, 51-53." (PMID 35414784, 2022). "Collectively, these findings indicate that USP11 promotes cytoplasmic p21 stabilization by deubiquitination in breast cancer cells." (PMID 35414784, 2022). "Supporting this, the addition of MG132 only marginally increased PRMT1 ubiquitylation, whilst protein levels of PRMT1 in two different breast cancer cell lines were unchanged after doxycycline-induced depletion or overexpression of USP11." (PMID 34728620, 2021). "USP11 targets both TGFBR1 and TGFBR2 for deubiquitination and enhances TGF-β signaling and metastasis, suggesting USP11 as a major therapeutic target for breast cancer." (PMID 33158118, 2020). "In breast cancer, USP11 promotes the TGF-β-induced epithelial–mesenchymal transition via altering the stability of TGFβ receptor type II." (PMID 31592114, 2019). "Tissue microarray together with public database analysis showed a significant correlation between high USP11 expression and poor prognosis in ER+ patients, supporting USP11 as a novel therapeutic target for breast cancer." (PMID 31504778, 2019). "In breast cancer tissue USP11 is seen to be upregulated and is correlated with the high level of XIAP." (PMID 29479529, 2018). "Future mechanistic studies will help to design inhibitors of USP11 and recognize it as a potential target in breast cancer." (PMID 29479529, 2018). "Underscoring the pro-survival role of USP11 in breast cancer, USP11 knockdown in normal mouse mammary epithelial cells (NMuMG) inhibited TGFβ-induced EMT." (PMID 25606592, 2014). "A recent study showed that breast cancer patients with high-level USP11 expression have higher rates of recurrence and poor survival outcomes when compared with low-level USP11 expressers." (PMID 25606592, 2014). "Whether USP11 plays a role in the treatment of breast cancer through this pathway, and whether there are other USPs that are critical for ferroptosis in breast cancer cells remains to be further investigated." (PMID 40083330, 2025). "As USP11 positively regulated the E-cadherin protein in mammary tumor cells, it was of interest to know whether USP11 regulated mammary tumor cell adhesion." (PMID 39270819, 2024). "To test this hypothesis, we checked the interaction between USP11 and E-cadherin in a human luminal-type breast cancer cell line, T47D." (PMID 39270819, 2024). "USP11 is, therefore, a tumor suppressor in luminal breast cancer." (PMID 39270819, 2024). "Next, we checked the mRNA expression of USP11 in the breast cancer patient sample sets." (PMID 39270819, 2024). "Our findings demonstrate that USP11 is a tumor suppressor for luminal breast cancer." (PMID 39270819, 2024). "Our findings provide compelling genetic and biochemical evidence that USP11 not only promotes DNA damage repair but also deubiquitinates E-cadherin and maintains the luminal feature of mammary tumor cells, thereby suppressing luminal breast cancer." (PMID 39270819, 2024). "Given the correlation between cytoplasmic p21 and USP11 in breast cancer tissues and cells, we hypothesized that cytoplasmic p21 might interact with USP11." (PMID 35414784, 2022). "Interestingly, the expression levels of p21 were highly consistent with the expression of USP11, and both p21 and USP11 were mainly located in the cytoplasm of all breast cancer cell lines evaluated." (PMID 35414784, 2022). "Moreover, increased p21 or USP11 expression was associated with higher clinical stages, and there was a significant positive correlation between p21 and USP11 in breast cancer tissues." (PMID 35414784, 2022).
breast cancer (continued). "Our results reveal an important mechanism regarding the regulation of cytoplasmic p21 stability, and indicate that the USP11-p21 axis in the cytoplasm could be a potential therapeutic target for breast cancer control." (PMID 35414784, 2022). "In this study, we found that USP11 was mainly located in the cytoplasm of breast cancer cells." (PMID 35414784, 2022). "The high expression of USP11 is also related to the poor prognosis of breast cancer." (PMID 35359344, 2022). "Since USP11 regulates cytoplasmic p21 stability, we hypothesized that USP11 may promote breast cancer cell proliferation through cytoplasmic p21." (PMID 35414784, 2022). "Additionally, USP11 interacts with XIAP to suppress apoptosis in breast cancer cells." (PMID 38722330, 2024). "Interestingly, USP11 may also inhibit breast cancer cell proliferation through deubiquitinating PTEN; however, no genetic evidence indicates that USP11 suppresses mammary tumorigenesis." (PMID 39270819, 2024). "Therefore, the development of drugs targeting USP11 to treat breast cancer is imminent." (PMID 35359344, 2022). "Furthermore, we characterized p21 and USP11 expression in different breast cancer cell lines." (PMID 35414784, 2022). "Moreover, previous evidences suggested USP11 could promote epithelial-to-mesenchymal transition to increase cell metastasis in ovarian cancer and breast cancer." (PMID 33685455, 2021). "However, little is known about the initiation of USP11 accumulation in breast cancer." (PMID 29479529, 2018). "Our findings support that USP11, a BRCA1-interacting protein, not only repairs DNA damage but also controls the differentiation of mammary tumor cells." (PMID 39270819, 2024). "USP11 has been identified to bind to the C-terminal of BRCA2 (2281-3418) and stabilize BRCA2 protein through deubiquitination, thus participating in DNA damage repair of breast cancer." (PMID 39617751, 2024). "In the present study, we found that overexpression of WT USP11, not mutant USP11, suppressed luminal breast cancer cell tumorigenesis." (PMID 39270819, 2024). "Based on our finding that NOTCH1 transcriptionally activates USP11 expression, it might be interesting to study the USP11-NOTCH1 positive feedback loop in other cancer types, including colorectal and breast cancer." (PMID 38007584, 2024). "Inhibition of USP11, USP4 and USP15 blocks TGFβ-mediated EMT and invasion in breast cancer." (PMID 25606592, 2014).
hepatocellular carcinoma (10 papers, 2021 to 2025). A malignant tumor that arises from hepatocytes. "On the other hand, USP11 significantly stimulates proliferation and metastasis of hepatocellular carcinoma cells both in vitro and in vivo." (PMID 38722330, 2024). "The results show that USP11 promotes or inhibits the progression and chemoresistance of different cancers, including colorectal, breast, ovarian, and hepatocellular carcinomas, via deubiquitinating several critical proteins of cancer-related pathways." (PMID 35715413, 2022). "The E2F1/USP11 positive feedback loop promotes hepatocellular carcinoma metastasis and inhibits autophagy by activating the ERK/mTOR pathway." (PMID 35383175, 2022). "Recently, it was shown that, in hepatocellular carcinoma, where high NF90 expression is associated with a poor prognosis, ubiquitin-specific protease 11 (USP11) promotes NF90 de-ubiquitination, thereby stabilizing it." (PMID 36362366, 2022). "Conversely, E2F1 also functions as a suppressor in hepatocellular carcinoma, interacting with ubiquitin specific peptidase 11 (USP11) to regulate the extracellular-signal regulated protein kinase/mammalian target of Rapamycin (ERK/mTOR) pathway to inhibit autophagy." (PMID 40886002, 2025). "In hepatocellular carcinoma research, it had been observed that USP11 might stabilize the protein level of the transcription factor E2F1, and E2F1 could also stimulate the transcription and translation of USP11." (PMID 39617751, 2024). "The role of USP11 in hepatocellular carcinoma has attracted the attention of numerous scholar, USP11 might be an excellent biomarker and therapeutic target for lots of hepatocellular carcinoma patients." (PMID 35715413, 2022). "Moreover, E2F1/USP11 further facilitates the progression of hepatocellular carcinoma by regulating the ERK/mTOR pathway to inhibit autophagy." (PMID 35715413, 2022). "Moreover, aberrant USP11 expression could accelerate proliferation and migration in Hepatocellular carcinoma." (PMID 39617751, 2024). "Additionally, USP11 could promote cell proliferation and metastasis via regulating nuclear factor 90 (NF90) in hepatocellular carcinoma." (PMID 33685455, 2021).